P2RY2 (purinergic receptor P2Y2)
Description:
Receptor for ATP and UTP coupled to G proteins that activate a phosphatidylinositol-calcium second messenger system. The affinity range is UTP = ATP > ATP-gamma-S >> 2-methylthio-ATP = ADP.
Synonyms: P2Y2; P2U1; P2RU1; P2U; HP2U; P2UR; P2Y2R
Tractability: Small molecule: a drug acting on it is in phase 2 or 3 trials; a high-quality ligand is known; it belongs to a druggable protein family. Antibody: its Gene Ontology location is reachable by antibodies, with high confidence; UniProt places it where antibodies can reach, with medium confidence; UniProt predicts a signal peptide or a membrane-spanning region. PROTAC: ubiquitination databases record sites on it; a small molecule that binds it is known.
Target class: Purine receptor; Small molecule receptor (family A GPCR); Membrane receptor; Family A G protein-coupled receptor; Nucleotide-like receptor (family A GPCR)
Gene: Protein-coding gene on chromosome 11 (73,216,664 to 73,242,427, forward strand). Ensembl gene ENSG00000175591.
Subcellular location: Cell membrane
Subcellular location (Human Protein Atlas): Cytosol
Pathways (Reactome):
Signal Transduction: G alpha (q) signalling events; P2Y receptors
Cellular responses to stimuli: High laminar flow shear stress activates signaling by PIEZO1 and PECAM1:CDH5:KDR in endothelial cells
Metabolism of proteins: Surfactant metabolism
Gene Ontology:
Molecular function: protein binding; A1 adenosine receptor binding; G protein-coupled UTP receptor activity; signaling receptor activity; G protein-coupled purinergic nucleotide receptor activity; G protein-coupled receptor activity
Biological process: cellular response to ATP; G protein-coupled purinergic nucleotide receptor signaling pathway; G protein-coupled receptor signaling pathway; intracellular monoatomic ion homeostasis; phospholipase C-activating G protein-coupled receptor signaling pathway; blood vessel diameter maintenance; positive regulation of mucus secretion
Cellular component: plasma membrane; membrane
Genetic constraint (gnomAD): Loss-of-function variants: 1 observed, 0.68 expected, observed/expected ratio (o/e) 1.47, 90% interval 0.31 to 1.92. That is too few expected variants to judge how well the gene tolerates losing a copy. Missense variants: 509 observed, 452.19 expected, observed/expected ratio (o/e) 1.13, 90% interval 1.05 to 1.21. Synonymous variants: 219 observed, 200.73 expected, observed/expected ratio (o/e) 1.09, 90% interval 0.98 to 1.22.
Homologues: Orthologues: chimpanzee P2RY2 (99% identical), macaque P2RY2 (97% identical), dog P2RY2 (89% identical), mouse P2ry2 (89% identical), rat P2ry2 (88% identical), guinea pig P2RY2 (88% identical), pig P2RY2 (85% identical), tropical clawed frog p2ry2 (52% identical), zebrafish p2ry2.1 (43% identical), zebrafish p2ry2.3 (41% identical), zebrafish p2ry2.2 (39% identical). Paralogues in human: P2RY4 (51% identical), P2RY6 (33% identical), P2RY1 (32% identical), OXGR1 (27% identical), SUCNR1 (26% identical), HCAR3 (22% identical), HCAR2 (22% identical), HCAR1 (21% identical), OXER1 (21% identical), GPR31 (21% identical), FFAR3 (20% identical), FFAR2 (20% identical), and 3 more.